LIN54 (lin-54 DREAM MuvB core complex component)
Description:
Component of the DREAM complex, a multiprotein complex that can both act as a transcription activator or repressor depending on the context. In G0 phase, the complex binds to more than 800 promoters and is required for repression of E2F target genes. In S phase, the complex selectively binds to the promoters of G2/M genes whose products are required for mitosis and participates in their cell cycle dependent activation. In the complex, acts as a DNA-binding protein that binds the promoter of CDK1 in a sequence-specific manner. Specifically recognizes the consensus motif 5'-TTYRAA-3' in target DNA.
Synonyms: CXCDC1; MIP120; DKFZp686L1814; JC8.6; TCX1
Tractability: PROTAC: UniProt records ubiquitination sites on it; ubiquitination databases record sites on it.
Gene: Protein-coding gene on chromosome 4 (82,909,973 to 83,012,983, reverse strand). Ensembl gene ENSG00000189308.
Subcellular location: Nucleus
Pathways (Reactome):
Cell Cycle: Cyclin A:Cdk2-associated events at S phase entry; Cyclin E associated events during G1/S transition; G0 and Early G1; G1/S-Specific Transcription; Polo-like kinase mediated events; Transcription of E2F targets under negative control by DREAM complex; Transcription of E2F targets under negative control by p107 (RBL1) and p130 (RBL2) in complex with HDAC1
Gene Ontology:
Molecular function: minor groove of adenine-thymine-rich DNA binding; protein binding; transcription regulatory region nucleic acid binding
Biological process: nucleosome organization; negative regulation of DNA-templated transcription; positive regulation of transcription by RNA polymerase II; regulation of DNA-templated transcription
Cellular component: RNA polymerase II transcription repressor complex; DRM complex; nucleoplasm; nucleus; RNA polymerase II transcription regulator complex
Genetic constraint (gnomAD): Loss-of-function variants: 6 observed, 58.06 expected, observed/expected ratio (o/e) 0.1, 90% interval 0.056 to 0.2. The upper end of that interval is the gene's LOEUF score, 0.2, which puts it in group 1 of 6, group 1 being the genes least tolerant of losing a copy. Missense variants: 461 observed, 770.93 expected, observed/expected ratio (o/e) 0.6, 90% interval 0.55 to 0.65. Synonymous variants: 226 observed, 276.84 expected, observed/expected ratio (o/e) 0.82, 90% interval 0.73 to 0.91.
Homologues: Orthologues: chimpanzee LIN54 (100% identical), macaque LIN54 (100% identical), dog LIN54 (99% identical), rabbit LIN54 (99% identical), pig LIN54 (97% identical), mouse Lin54 (97% identical), rat Lin54 (96% identical), guinea pig LIN54 (95% identical), tropical clawed frog lin54 (72% identical), zebrafish lin54 (61% identical). Paralogues in human: TESMIN (24% identical).
Diseases named in the same sentence as LIN54 in open-access papers:
LIN54 is named in the same sentence as 6 diseases in open-access papers, as found by Europe PMC text mining. Sharing a sentence is not in itself a finding about the gene and the disease. The quoted sentences say what the papers report.
breast carcinoma (1 paper, 2025). "With respect to combination therapy, in breast cancer, it has been demonstrated that activation of the FOXM1–CDK1 positive feedback loop induces replication stress, and that targeting the MMB–FOXM1 complex (e.g., LIN54) contributes to enhancing the efficacy of CHK1 inhibitors." (PMID 41413918, 2025).
embryonal carcinoma (1 paper, 2011). A non-seminomatous malignant germ cell tumor characterized by the presence of large germ cells with abundant cytoplasm resembling epithelial cells, geographic necrosis, high mitotic activity, and pseudoglandular and pseudopapillary structures formation. "In mouse embryonal carcinoma cells knock-down of lin-9 or lin-54 resulted in significant cell cycle defects, while knock down of lin-37 or lin-52 had no such effects." (PMID 21570388, 2011).
tumor (4 papers, 2015 to 2025). "First we analysed the expression of MMB and DREAM complex components and found that amongst tumours, reduced levels of LIN54 are generally found in tumours but lower levels are indicative of late stage disease in patients with late T stage tumours and local metastases." (PMID 25889361, 2015). "The synMuv B genes encode homologues of the dREAM complex, which are conserved across animals and plants, including the LIN-35/retinoblastoma (Rb) tumor suppressor, and the Rb complex components LIN-53 /RbAp48, LIN-37/MIP40, LIN-54/MIP120, DPL-1 /DP, LIN-9/MIP130." (PMID 39879188, 2025).
cardiovascular disease (1 paper, 2022). "Since the CM promoter interaction map linked SNPs to target genes relevant with cardiovascular disease, LIN54, COQ2, and FAM175A were prioritized for further TF correlation analysis." (PMID 36568976, 2022).
LIN54 also shares sentences with these, for which no sentence is quoted: cancer (1 paper); pancreatic cancer (1).